MTATP8P1 (MT-ATP8 pseudogene 1)
Gene: Unprocessed pseudogene on chromosome 1 (633,535 to 633,741, forward strand). Ensembl gene ENSG00000240409.
Diseases named in the same sentence as MTATP8P1 in open-access papers:
MTATP8P1 is named in the same sentence as 3 diseases in open-access papers, as found by Europe PMC text mining. Sharing a sentence is not in itself a finding about the gene and the disease. The quoted sentences say what the papers report.
neuropathy (1 paper, 2024). A disorder affecting the nervous system that manifests with pain, tingling, numbness, and/or muscle weakness. "MTATP8P1 is a factor involved in mitochondrial ATP synthesis-coupled proton transport and periodic paralysis associated with cardiac myopathy and neuropathy." (PMID 39684854, 2024).
cancer (1 paper, 2023). A tumor composed of atypical neoplastic, often pleomorphic cells that invade other tissues. "Given this evidence, further research is needed to investigate the role of AKR1B15, MTATP8P1, and SP6 in cancer." (PMID 38086955, 2023). "However, there is currently no research on the role of AKR1B15, MTATP8P1, and SP6 in cancer." (PMID 38086955, 2023).
MTATP8P1 also shares sentences with these, for which no sentence is quoted: periodic paralysis (1 paper).